COL12A1 (collagen type XII alpha 1 chain)
Description:
Type XII collagen interacts with type I collagen-containing fibrils, the COL1 domain could be associated with the surface of the fibrils, and the COL2 and NC3 domains may be localized in the perifibrillar matrix.
Synonyms: COL12A1L; BA209D8.1; BTHLM2; DJ234P15.1; EDSMYP; UCMD2
Tractability: Antibody: its Gene Ontology location is reachable by antibodies, with high confidence; UniProt places it where antibodies can reach, with medium confidence; UniProt predicts a signal peptide or a membrane-spanning region. PROTAC: ubiquitination databases record sites on it.
Gene: Protein-coding gene on chromosome 6 (75,084,326 to 75,206,267, reverse strand). Ensembl gene ENSG00000111799.
Subcellular location: Secreted, extracellular space, extracellular matrix
Subcellular location (Human Protein Atlas): Vesicles; Cytosol; Predicted to be secreted
Pathways (Reactome):
Extracellular matrix organization: Assembly of collagen fibrils and other multimeric structures; Collagen biosynthesis and modifying enzymes; Collagen chain trimerization; Collagen degradation
Gene Ontology:
Molecular function: extracellular matrix structural constituent conferring tensile strength
Biological process: endodermal cell differentiation; collagen fibril organization; tissue development
Cellular component: extracellular exosome; extracellular matrix; extracellular region; extracellular vesicle; collagen type XII trimer; endoplasmic reticulum lumen; interstitial matrix
Genetic constraint (gnomAD): Loss-of-function variants: 102 observed, 320.67 expected, observed/expected ratio (o/e) 0.32, 90% interval 0.27 to 0.38. The upper end of that interval is the gene's LOEUF score, 0.38, which puts it in group 1 of 6, group 1 being the genes least tolerant of losing a copy. Missense variants: 3,075 observed, 3,667.7 expected, observed/expected ratio (o/e) 0.84, 90% interval 0.81 to 0.86. Synonymous variants: 1,297 observed, 1,297.5 expected, observed/expected ratio (o/e) 1, 90% interval 0.95 to 1.05.
Homologues: Orthologues: chimpanzee COL12A1 (99% identical), macaque COL12A1 (99% identical), rabbit COL12A1 (95% identical), dog COL12A1 (95% identical), pig COL12A1 (94% identical), mouse Col12a1 (92% identical), rat Col12a1 (92% identical), guinea pig COL12A1 (92% identical), tropical clawed frog col12a1 (73% identical), zebrafish col12a1b (61% identical), zebrafish col12a1a (60% identical). Paralogues in human: COL14A1 (27% identical), COL6A3 (18% identical), COL6A6 (13% identical), COL6A5 (12% identical), VWA2 (6% identical), MATN2 (6% identical), COCH (5% identical), MATN4 (5% identical), MATN1 (5% identical), VIT (4% identical), MATN3 (3% identical), VWA1 (3% identical).
Diseases named in the same sentence as COL12A1 in open-access papers:
COL12A1 is named in the same sentence as 102 diseases in open-access papers, as found by Europe PMC text mining. Sharing a sentence is not in itself a finding about the gene and the disease. The quoted sentences say what the papers report.
gastric cancer (22 papers, 2010 to 2025). A primary or metastatic malignant neoplasm involving the stomach. "COL12A1 encodes for a protein that is a fibril‐associated collagen and is a potential prognostic and therapeutic target in gastric cancer." (PMID 40998421, 2025). "High COL12A1 expression is associated with poor overall survival and progression-free survival in patients with gastric cancer." (PMID 35407556, 2022). "COL12A1 was upregulated in gastric cancer and positively associated with tumor invasion and clinical stage and was also significantly correlated with IGFBP7 (|r| = 0.426016684, p = 5.75765E-18)." (PMID 34745945, 2021). "COL12A1 is associated with joint anomalies, gastric cancer, myopathies, ECM defects, and chondromyxoid fibroma." (PMID 32982747, 2020). "COL12A1 is diagnosed with the pathogenesis of gastric cancer, but this gene may be associated with the pathogenesis of BRCA." (PMID 31311202, 2019). "Among the genes found exclusively in the good responder group, COL12A1 upregulation has been identified as a predictor of poor prognosis in human patients with pancreatic adenocarcinoma and gastric cancer." (PMID 40320296, 2025). "Knocking down both IDO1 and COL12A1 in gastric cancer cells (SGC-7901) led to greater ERK phosphorylation inhibition and reduced cell migration." (PMID 39048763, 2024). "Through GEPIA database, we found that COL1A1, COL4A1 and COL12A1 was differentially expressed in patients with gastric cancer, significantly suggesting a poor prognosis." (PMID 37700383, 2023). "In this study, bioinformatics analysis was conducted to clarify the expression level and clinical significance of COL12A1 in gastric cancer, and in-vitro and in-vivo experiments were performed to further explore the role of COL12A1 in gastric cancer." (PMID 37700383, 2023). "COL12A1 is aberrantly upregulated in human malignancies including gastric cancer, colon cancer, colorectal cancer and pancreatic adenocarcinoma, and its upregulation correlated with tumor progression and poor prognosis." (PMID 36694230, 2023). "Of note, recent reports have underscored the pivotal roles of these genes in tumorigenesis, invasion, and prognosis (e.g., COL12A1 in gastric cancer, FAT1, and FBN1/2 in HCC)." (PMID 36900398, 2023). "Through GEPIA database, we found that COL1A1, COL4A1 and COL12A1 were differentially expressed in patients with gastric cancer, significantly suggesting a poor prognosis." (PMID 37700383, 2023). "The overexpression of COL12A1 is also associated with invasion, lymph node metastasis, distant metastasis and an advanced TNM stage of gastric cancer." (PMID 34094925, 2021). "For example, IDO1 and COL12A1, which were found to synergistically promote gastric cancer metastasis, appear to be promising targets for the treatment of gastric cancer." (PMID 34968391, 2021). "Hub genes of COL1A1, COL4A1, COL12A1, and PDGFRB were overlapped in both PPI hub gene list and the turquoise module with significant association with the prognosis in gastric cancer." (PMID 35111208, 2021). "The best three single-gene discriminators are SERPINH1, BGN and COL12A1 for stomach cancer, having 99.1%, 98.2% and 98.2% classification accuracy on the training set and 94.2% and 96.7%, 88.4% and 93.3%, and 84.1% and 75.8% on the two test sets, respectively." (PMID 21060876, 2010). "COL12A1 was also reported to promote gastric cancer metastasis via the MAPK pathway." (PMID 40565351, 2025). "Moreover, our experiments provide novel evidence that JYQHD is a potential agent in gastric cancer therapy, and COL12A1 is a potentially valuable gene that regulates ferroptosis." (PMID 37700383, 2023). "Multiple data revealed that COL12A1 was highly denoted in gastric cancer." (PMID 37700383, 2023). "Based on the bioinformatics analysis and literature search, we hypothesized that COL12A1 was one of the potential target genes of JYQHD, and COL12A1 could regulate the ferroptosis pathway in gastric cancer." (PMID 37700383, 2023).
gastric cancer (continued). "COL12A1 was highly expressed in gastric cancer tissues, indicating poor prognosis." (PMID 37700383, 2023). "Furthermore, it was reported that COL12A1 positively promoted gastric cancer metastasis via MAPK pathway." (PMID 35399719, 2022). "However, there were few reports on the basic studies of COL12A1 in gastric cancer." (PMID 37700383, 2023). "COL12A1 has been reported as a poor prognostic indicator for cancers including BRCA, gastric cancer (GC) and cholangiocarcinoma." (PMID 38235137, 2023). "According to Network Pharmacology analysis, COL12A1 and COL1A1 were the target genes of gastric cancer." (PMID 37700383, 2023). "COL12A1 is reported to be expressed by both stroma and tumor cells in STAD and is expressed in gastric cancer cell lines." (PMID 35120467, 2022). "For early stomach cancer, the best three 1-gene discriminators are also SERPINH1, BGN and COL12A1, respectively." (PMID 21060876, 2010). "First, we found that COL5A2, COL12A1, BGN and THBS2 were highly expressed in gastric cancer." (PMID 36447214, 2022).
breast carcinoma (18 papers, 2013 to 2025). "Three novel miR-26b targets were identified (TNKS1BP1, CPSF7, COL12A1), and the expression of each in cancer stroma shown to be significantly associated with breast cancer recurrence." (PMID 27078844, 2016). "COL12A1 has been shown to be a statistically significant representation of myoepithelial types, and loss of myoepithelial function is a key step in breast cancer progression." (PMID 25593998, 2014). "Moreover, survival analysis via Kaplan-Meier plotter done by other researchers found that gene COL12A1 was negatively associated with the prognosis of breast cancer patients." (PMID 39445291, 2024). "Because mutation of this gene is more prevalent in African American breast cancer patients, it is reasonable to suggest that the COL12A1 gene may be associated with the increased mortality in African American breast cancer patients." (PMID 39445291, 2024). "For instance, type XII collagen alpha 1 chain (COL12A1) is implicated in cancer cell progression and metastasis and it has been identified as a potential marker of poor prognosis in patients with breast cancer, colorectal cancer, pancreatic adenocarcinoma, and ovarian cancer." (PMID 39769286, 2024). "TNC, COL18A1 and COL12A1 gene expression characterize fibroblasts known as ECM-CAF (Extracellular Matrix-Cancer Associated Fibroblasts) which participates in the aberrant remodeling of the extracellular matrix in breast cancer." (PMID 39239354, 2024). "In addition, COL12A1 is identified as one novel target of miR-26b in carcinoma-associated fibroblasts of breast cancer." (PMID 27802793, 2017). "In addition, three novel miR-26b targets were identified (TNKS1BP1, CPSF7, COL12A1) and the expression of each in cancer stroma was shown to be significantly associated with breast cancer recurrence." (PMID 23939832, 2013). "Proteomics and single-cell transcriptomics analyses of genetically engineered mouse models identified increased levels of COL12A1 in breast cancers compared to normal mammary tissues." (PMID 40565351, 2025). "CD34– myCAFs express high levels of Lrrc15+, a marker of immunosuppressive fibroblasts that mediates resistance to immune checkpoint blockade in pancreatic cancer, and Col12a1, identified as a potential driver of invasion in breast cancer." (PMID 40216939, 2025). "We subsequently assessed the set of INHBA-related genes in breast cancer and found that genes encoding collagens COL10A1, COL12A1, COL5A2 and COL11A1 were associated with INHBA expression." (PMID 41008625, 2025). "Further, in patients with breast cancer high expression of COL12A1 predicted poor response to immunotherapy treatment." (PMID 39048763, 2024). "Another YAP1 target gene, COL12A1 (collagen type 12 alpha one chain), has been shown to play a role in tumor invasion and migration in gastric, colorectal and breast cancer." (PMID 35407556, 2022). "COL12A1 encodes the alpha chain of type XII collagen, which has been found to be a regulatory target of miR-26b and is predictive of breast cancer recurrence." (PMID 27467526, 2016). "COL12A1 was found to play an important role in promoting breast cancer metastasis." (PMID 40565351, 2025). "The team reported that collagen type XII strongly correlated with tumor progression and confirmed results of a prior study conducted in patients with breast cancer demonstrating an increased expression of COL12A1 in breast cancers as compared with normal mammary tissue." (PMID 36918099, 2023). "For each gene, high expression, as seen in 26bk/d cells, was significantly associated with increased rates of recurrence (log rank, TNKS1BP1 p = 0.002, CPSF7 p = 0.007, COL12A1 p = 0.043), implicating them, and by inference miR-26b, as stromal determinants of breast cancer outcome." (PMID 23939832, 2013). "COL12A1 and THBS2 are components of extracellular matrix (ECM) proteins that significantly upregulate in breast cancer compared with normal breast tissue." (PMID 39954675, 2025).
breast carcinoma (continued). "COL12A1 overexpression has been detected and was predictive of poor prognosis in multiple cancer types including colorectal (CRC), gastric, breast cancer, renal, ovarian and pancreatic cancer." (PMID 39048763, 2024). "COL12A1 upregulation has also been correlated with metastasis, such as lymph nodes, and reduced patients’ survival with human epidermal growth factor receptor 2 (HER2)-positive breast cancer." (PMID 39769286, 2024). "Interestingly, expression of KLK5 was high in basal-like and normal-like breast cancer subtypes with a reduction in levels in luminal B. There was reduced expression in normal tissue and basal subtypes with higher expression in luminal (ER+) and Her-2 subtypes for ITGB5, EZR, COL12A1, and COL24A1." (PMID 25593998, 2014).
colorectal cancer (12 papers, 2012 to 2023). A primary or metastatic malignant neoplasm that affects the colon or rectum. "Although previous studies revealed that COL12A1 was closely related to tumor migration, invasion and metastasis in breast and colorectal cancer, but the underlying mechanisms were still unclear." (PMID 31315643, 2019). "Enrichment analysis of genes in the COL12A1 neighborhood in colorectal cancer identified focal adhesion and PI3K-AKT signaling pathways." (PMID 36765749, 2023). "Collagen type XII is a homodimer found in association with type I collagen-containing fibrils, with a known amplification of the COL12A1 gene and overexpression in colorectal cancer." (PMID 36765749, 2023). "Our paper identified COL12A1 as oncogenic gene for colorectal cancer by integrated bioinformatics analysis." (PMID 32356618, 2020). "In comparison to a recent analysis utilizing MutSigCV, our methodology identified other colorectal cancer related genes such as COL12A1, MLL2, FAT4m and ARID1A." (PMID 26379039, 2015). "In a complementary fashion, gene expression meta-analysis revealed that COL12A1 is also an upregulated gene in colorectal cancer." (PMID 22408128, 2012). "(2020) reported that there is a negative association between COL12A1 methylation and colorectal cancer." (PMID 37361568, 2023). "Lower COL12A1 could inhibit the proliferation and migration of colorectal cancer cells, which may be a new biomarker for prognosis." (PMID 37312060, 2023). "We demonstrated the prognosis and function of COL12A1 in colorectal cancer." (PMID 32356618, 2020). "Abnormal COL12A1 expression is associated with carcinogenesis of colorectal cancer (CRC), but its clinical value and function have not yet been analyzed." (PMID 32356618, 2020). "In addition, increased COL12A1 expression has recently been noted at colorectal cancer invasive fronts, implicating COL12A1 in invasion." (PMID 23939832, 2013). "Our method is able to identify the known driver genes for colorectal cancer; additionally, we also identified some driver genes not found by the MutSigCV study, such as COL12A1, MLL2, FAT4 and ARID1A." (PMID 26379039, 2015). "Interestingly, we found that the 1009 predicted protein targets of SNT included CRP but not COL12A1 in BATMAN; COL12A1 may not have been studied very much, as only a few studies have shown its association with Colorectal Cancer and colon cancer." (PMID 32982747, 2020).
pancreatic cancer (9 papers, 2020 to 2025). "Bioinformatic analysis indicated COL12A1 has a prognosis effect in pancreatic cancer, but the mechanism underlying the effect of COL12A1 in PDAC progression is still unelucidated." (PMID 36900272, 2023). "Our study demonstrated the potential diagnostic and prognostic value of COL12A1 expression in pancreatic cancer and elucidated the possible molecular mechanism underlying its role in promoting the development of pancreatic cancer in CAFs." (PMID 36900272, 2023). "Our study demonstrated the potential diagnostic and prognostic value of COL12A1 expression in pancreatic cancer and elucidated the molecular mechanism underlying its role in CAFs and promoting the development of pancreatic cancer." (PMID 36900272, 2023). "Based on the results from expression and correlation analysis, NAMPTP1/HCG11-hsa-miR-26b-5p-COL12A1 competing endogenous RNA (ceRNA) sub-network was associated with the prognosis of pancreatic cancer." (PMID 33027767, 2020). "Therefore, we demonstrated the potential prognostic and target therapy value of COL12A1 expression in pancreatic cancer and elucidated the molecular mechanism underlying its role in CAFs." (PMID 36900272, 2023). "Thirty-one pairs of clinical specimens were used to verify that COL12A1 expression in pancreatic cancer tissue was significantly higher than that in para-cancerous tissue." (PMID 36900272, 2023). "Univariable and multivariable cox regression analyses showed that the COL12A1 expression level was an independent determinant to predict the outcome of pancreatic cancer patients." (PMID 36900272, 2023). "Analysis of The Cancer Genome Atlas (TCGA) dataset and investigation of our clinical tissue samples indicated that COL12A1 expression was aberrantly highly expressed in pancreatic cancer." (PMID 36900272, 2023). "Survival and COX regression analyses revealed the significant clinical prognostic value of COL12A1 expression in pancreatic cancer." (PMID 36900272, 2023). "Analysis of the TCGA dataset implied that COL12A1 has an important role in pancreatic cancer prognosis." (PMID 36900272, 2023). "Performing bioinformatic analysis, Jing and Chen indicated that COL12A1 was the potential prognosis biomarker in pancreatic cancer." (PMID 36900272, 2023). "In this research, we systematically analyzed the mechanism involved in using COL12A1 as a therapy target and prognosis biomarker for pancreatic cancer." (PMID 36900272, 2023). "Among them, one novel miRNA (hsa-mir-4772) and two novel genes (COL12A1 and COL5A2) associated with pancreatic cancer have great potential to be used as prognostic factors and therapeutic targets for this tumor." (PMID 34094925, 2021). "The hsa-miR-26b-5p-COL12A1 axis showed a potential in suppressing the progression of pancreatic cancer." (PMID 33027767, 2020). "The ROC curve indicated that COL12A1 might be a predictor for the survival rate of pancreatic cancer patients." (PMID 36900272, 2023). "Therefore, we focused on COL12A1 to explore its mechanism in the occurrence and development of pancreatic cancer." (PMID 36900272, 2023). "Several published papers have already indicated that COL12A1 might be the key prognosis biomarker for pancreatic cancer." (PMID 36900272, 2023). "TISCH checking indicated that COL12A1 is primarily expressed in cancer-associated fibroblasts but not in tumor cancer cells or other immune cells in TME for pancreatic cancer." (PMID 36900272, 2023). "Furthermore, the results from our cell line analysis indicated that the COL12A1 expression in the extracted para-cancerous fibroblasts was significantly higher than that in pancreatic cancer cells." (PMID 36900272, 2023). "Interestingly, stage IIB resulted in an increased expression of genes encoding constituents of collagen X (COL10A1), collagen X1 (COL11A1), and collagen XII (COL12A1) isoforms, which have been reported to be prognostic markers of pancreatic cancer metastasis." (PMID 35565326, 2022).